Y_RNA (Y RNA )
Gene: Miscellaneous RNA gene on chromosome 11 (13,686,550 to 13,686,658, reverse strand). Ensembl gene ENSG00000200685.
Homologues: Orthologues: chimpanzee Y_RNA (100% identical), guinea pig Y_RNA (79% identical), macaque Y_RNA (75% identical). Paralogues in human: RNY1 (85% identical), Y_RNA (83% identical), Y_RNA (82% identical), Y_RNA (81% identical), Y_RNA (80% identical), Y_RNA (79% identical), Y_RNA (78% identical), RNY1P7 (77% identical), Y_RNA (77% identical), RNY1P11 (76% identical), RNY1P12 (76% identical), Y_RNA (76% identical), and 92 more.